HMGB1 (high mobility group box 1)
Diseases named in the same sentence as HMGB1 in open-access papers (continued):
Sharing a sentence is not in itself a finding about the gene and the disease.
cancer (continued). "Strikingly, HMGB1 was found consistently positively correlated with the SRSFscore in all cancer types." (PMID 38015716, 2023). "First, to confirm that the HBHP peptide is able to remove HMGB1 from CM of cells treated with anti-cancer drugs, we precipitated HBHP and HBHP-scr using Neutravidin Agarose beads." (PMID 37880798, 2023). "Recent studies suggest that the secretion of high-mobility group box 1 protein (HMGB1), one of the products of apoptosis by ferroptosis, contributes to the activation of immune cells surrounding cancer cells." (PMID 37108220, 2023). "The difference in transcript levels among the eight cancer cell lines was the smallest for HMGB1, with a Ct of 1.59, corresponding to a 3-fold difference among cell lines." (PMID 37627239, 2023). "The major signal transduction axis of HMGB1 in cancer seems to be mediated through the receptor for advanced glycation end products (RAGE) and toll-like receptor (TLR)-4." (PMID 37511951, 2023). "For example, the cytokine HMGB1 released by cancer cells contributes to cancer development by promoting tolerogenic DC differentiation and the suppression of anti-tumoral T cells." (PMID 36993954, 2023). "Cancer eradication requires HMGB1 to bind to Toll-like receptor 4, activating immune cells through signaling pathways." (PMID 37291495, 2023). "One study has reported the increase of calreticulin exposure on the surface of ferroptotic cancer cells, which, combined with higher emissions of HMGB1 and ATP, induced the activation and maturation of BMDCs to exert an antitumor effect." (PMID 37325669, 2023). "Anthracyclines can trigger exposure to CRT, as well as HSP70 and HSP90 expression, which involves translocation of these markers to the cell surface, and thus induces anti-cancer immune responses and HMGB1 release." (PMID 37153795, 2023). "We next assessed expression of HMGB1 in polyps displaying a focus of cancer (termed cancer polyps, CaP)." (PMID 36980751, 2023). "Our study preliminarily explored the interaction between TAMs and cancer cells based on HMGB1 in CRC." (PMID 36709284, 2023). "Gold-standard approaches to prediction of the ICD-inducing capacity of chemotherapeutic agents appear to rely on CRT exposure, ATP secretion, and HMGB1 release by human cancer cells." (PMID 37153795, 2023). "The highest sensitivities for cancer detection at 90% specificity versus benign diseases were achieved using HMGB1 with 41.3% and the HMGB1/sRAGE ratio with 39.2%, followed by sRAGE with 18.9%." (PMID 37894448, 2023). "Both HMGB1 and sRAGE are involved in inflammation and in metabolism within the microenvironment of malignant tumors." (PMID 37894448, 2023). "In the current study, we further identified that human A549 and T24 cancer cells promoted PMA-induced NET formation from human neutrophils involving released HMGB1 due to the suppressive effect of HMGB1-neutralizing IgG." (PMID 36012397, 2022). "This study also analyzed the relationship between NOL7 expression and the expression of 60 common immune checkpoint genes, and notably found that NOL7 expression was positively correlated with HMGB1 in most cancer types." (PMID 36077008, 2022). "Extracellular HMGB1 can facilitate the processing and presentation of antigens by DCs, while intracellular HMGB1 can promote cancer cell growth and invasion, and resist therapy." (PMID 36619616, 2022). "In our study, we made a connection between the Vanguard, HMGB1, and the genomic stability of cancer cells." (PMID 36047643, 2022).
cancer (continued). "Production of HMGB1 by Th can lead to cancer through several interactions, such as promoting the production of dendritic cells, which leads to more production of all cytokines, or through helper T-cells which are similarly cytokine producers." (PMID 35294447, 2022). "HMGB1 has complex roles in cancer progression, depending on its subcellular localization, post-transcriptional modification and binding receptors." (PMID 35493517, 2022). "On the other hand, some inflammatory factors (IL-1β, IL18, and HMGB1) released by pyroptosis can trigger the activation of cancer-promoting signaling pathways including ERK1/2, p38 MAPK, and VEGF pathways." (PMID 35368686, 2022). "In this study, we show that the deletion of the C-terminal acidic tail of HMGB1 increases its antitumor activity towards a large panel of cancer cells, including cells that are otherwise resistant to DNA-targeting agents." (PMID 35887213, 2022). "HMGB1 showed a positive association with CDK1 (R = 0.51), SSRP1 (R = 0.57), H2AFV (R = 0.53), and HMGB2 (R = 0.57) genes in several cancer types and these data were visualized as a heatmap." (PMID 36230798, 2022). "The high mobility group box 1 protein (HMGB1), an essential protein required for cancer cell immunogenicity, is a crucial DAMP that promotes antigen presentation by dendritic cells (DCs) to T cells." (PMID 36158661, 2022). "For example, HMGB1 overexpression was correlated with poorer OS in several cancers when detected by immunohistochemistry in tissues and enzyme-linked immunosorbent assay in serum." (PMID 36142453, 2022). "Meanwhile, depletion of HMGB1 and ly294002 promoted apoptosis and arrested the cancer cells in G0/G1 cell cycle with the decreased expression of Cyclin D1 and CDK4 and improved P16." (PMID 36260180, 2022). "Our results demonstrate that the deletion of the C-terminal tail of HMGB1 increases its activity towards a large panel of cancer cells including cells resistant to DNA-targeted chemotherapy without affecting the viability of normal immortalized fibroblasts." (PMID 35887213, 2022). "These include ATP, calreticulin (CRT), high-mobility group Box 1 (HMGB1), heat shock proteins (HSPs) 70 and 90, and cytokines/chemokines promoting the recruitment and maturation of antigen-presenting cells by cancer cells that are in the process of dying." (PMID 35562364, 2022). "Glycyrrhizin and licorice flavonoids suppress cancer initiation through complex effects on macrophages that involve inhibition of high-mobility group box 1 (HMGB1)-TLR4-NF-kB signaling, proinflammatory cytokines, COX-2, and M2 polarization." (PMID 35681791, 2022). "In cancer cells, HMGB1 phosphorylation at serine residues 35, 39, 42, 53 and 181 are critical for cytoplasmic localization of HMGB1." (PMID 35632744, 2022). "To further interrogate the genetic structure variation status of HMGB1 with various cancer types, we obtained the highest HMGB1 alteration frequency value of greater than 8% for DLBC, followed by GBM." (PMID 36230798, 2022). "In a hypoxic milieu, the abundance of RAGE ligands is increased, particularly HMGB1, which is released by either infiltrating leukocytes or cancer cells themselves, under hypoxic conditions." (PMID 35727208, 2022). "High Mobility Group Box 1 (HMGB1) protein has been described as a consensus marker for immunogenic cell death (ICD) in cancer." (PMID 34671818, 2022). "After exposure to doxorubicin (DOX), there is an increase in extracellular HMGB1 and this HMGB1 will function in a paracrine manner to induce chemoresistance of cancer cells that survive nearby." (PMID 35340325, 2022). "The results showed that overexpression of HMGB1 in ESCC reported to have a significant correlation with the cancer progression." (PMID 35829833, 2022).
cancer (continued). "Both of those studies focused on the role of RAGE of HMGB1 in cancer cachexia-induced muscle atrophy." (PMID 36497194, 2022). "We aimed to analyze the potential conserved oncogenic role of HMGB1 in 33 types of cancer through the TCGA, GEO, and Oncomine databases." (PMID 36230798, 2022). "When cancer cells undergo necrosis, they release high mobility group box-1 (HMGB-1) which activates dendritic cells (DCs)." (PMID 35015785, 2022). "Adjuvanticity is modulated by DAMPs such as calreticulin and HMGB1 which act as adjuvants to boost the anti-cancer immune response." (PMID 35903697, 2022). "Initially, the expression pattern of HMGB1 was analysed across various cancer types of TCGA using TIMER2." (PMID 35765707, 2022). "We first obtained the correlation of HMGB1 DNA methylation with pathogenesis in various cancer types via the TCGA project." (PMID 36230798, 2022). "In addition, even among low‐grade cancer patients, blue‐collar industries such as manufacturing and constructions tend to be associated with higher risks for histological malignancies confirmed by HMGB1, after adjusting for behavioral and chronic inflammatory factors." (PMID 35712799, 2022). "One of these proteins, extracellular S100A4, has been shown to play unusual roles in cancer progression that are very similar to the roles of HMGB1 and S100A8/A9." (PMID 36142212, 2022). "A study has shown that HMGB1 regulates VEGF-D to mediate the formation of cancer blood vessels, thus promoting cancer." (PMID 35359956, 2022). "Our study therefore implies that differences in HMGB1 expression contribute to natural histone density variation across cancer cell lines." (PMID 36030322, 2022). "HMGB1 released from cancer cells killed by ferroptosis can stimulate inflammatory responses of macrophages when connecting with AGER." (PMID 35432535, 2022). "One of these chromatin proteins is HMGB1, which is required to maintain high histone levels in cancer cells." (PMID 36030322, 2022). "Extracellular HMGB1, released by cancer cells, binding RAGE can induce autophagy activity in nearby cells." (PMID 35269471, 2022). "High-mobility group box 1 (HMGB1) is released by cancer cells during ferroptosis in an autophagy-dependent mechanism." (PMID 35488303, 2022). "This is further substantiated by the release of immunogenic cell death marker HMGB1 after exposure of cancer cells to jin-3 reovirus." (PMID 34135475, 2022). "We unveil strong evidence that soluble HMGB1 released from cancer cells can drive the proliferating B cells into a proangiogenic state for mediating VEGF-dependent angiogenesis." (PMID 34617194, 2022). "It is consistent with our assumptions of parameters, as HMGB1 is mainly secreted by cancer and necrotic cells in the cancer microenvironment." (PMID 36294824, 2022). "Extracellular HMGB1 promotes cancer progression and has potential as a novel treatment target in GC cells for rTM." (PMID 35328684, 2022). "Plasma membrane exposure of CRT, the release of ATP, and the exodus of HMGB1 from dying cancer cells through membranolytic action were detected." (PMID 36012593, 2022). "Based on the powerful immune-modulatory function of HMGB1, immune or combination therapies developed for HMGB1 are of great significance to improve the prognosis and prolong the survival of cancer patients." (PMID 35637945, 2022). "Among a wide spectrum of TLR4 ligands, high-mobility group box 1 (HMGB1) was known for its prominent role in regulating both immune responses and cancer progression." (PMID 36542153, 2022). "Recently, HMGB1 was reported to regulate several cancer-related signal paths, for example, NF-κB signaling and PI3K/AKT/mTOR pathway." (PMID 35562734, 2022). "Emerging evidence suggests that DAMPs, including HMGB1, play an important role in initiating and sustaining chronic inflammation that impairs antitumor immunity and promotes cancer progression." (PMID 36050306, 2022).
cancer (continued). "HMGB1 has several important roles in inflammation and cancer and appears to play paradoxical roles during the development and therapy of cancer according to subcellular locations, receptors, and expression levels." (PMID 35610613, 2022). "Here, we discovered a 3-styrylchromone derivative C6, which possessed both potent anti-inflammatory and anti-cancer activities by blocking the HMGB1-RAGE-ERK1/2 axis." (PMID 35408786, 2022). "It has been reported that high mobility group box-1 protein (HMGB1) secreted during tumorigenesis induces the degradation of host muscle tissues to supply glutamine to cancer cells as an energy source." (PMID 35574329, 2022). "Our subsequent in vitro analyses therefore utilized 6 days co-culture systems to further characterize the mechanistic link between B cells and cancer-derived HMGB1, as well as their potential roles in orchestrating tumorigenesis and progression in ESCC." (PMID 34617194, 2022). "Early evidence of DAMP release from ferroptotic cells indicated that MEFs and cancer cells released HMGB1 in a mechanism dependent on the activation of the autophagic machinery." (PMID 35065965, 2022). "HMGB1 is one of the highly conserved chromatin-associated proteins containing HMG-box domains and has been reported to be abnormally expressed in diverse cancers." (PMID 35145563, 2022). "The authors reported that patients whose cancer exhibited cytosolic HMGB-1 before neoadjuvant chemoradiotherapy had a better clinical outcome." (PMID 36015189, 2022). "Among the DAMPs, the main actors are surface-exposed calreticulin (CRT), secreted adenosine triphosphate (ATP) and passively released HMGB1: they represent the main hallmarks of immunogenic cell death (ICD) of cancer cells." (PMID 36012593, 2022). "Although the mechanism is not clear, we demonstrated that itaconate causes cell death and DAMP (HMGB1 and SQSTM1) release, which is consistent with recent studies on the cytotoxicity of itaconate on cancer cells." (PMID 35769880, 2022). "Intracellular and extracellular HMGB1 have both been reported to contribute to carcinogenesis, cancer progression, and metastasis." (PMID 35328684, 2022). "In clinical practice, radiotherapy and chemoradiotherapy were shown to induce the exposure of the ICD-related DAMPs calreticulin, HSP70 and HMGB1 when applied either as a pre- or post-operative protocol of different cancers." (PMID 36015189, 2022). "Understanding the molecular underpinnings of HMGB1′s role as a protumor protein in cancer requires additional research." (PMID 36428714, 2022). "As this is a pan‐cancer analysis and the presented results show that the function of HMGB1 is different in different cancer types, and the relationship of prognosis are different from the results of immune infiltrations." (PMID 35765707, 2022). "This indicates that cancer cells undergoing ferroptosis release HMGB1, an important protein necessary to make cancer cells immunogenic, and DAMPs, an endogenous molecule released from injured or stressed cells." (PMID 36060256, 2022). "The interactions between immune cells, cancer cells, necrotic cells, and adipocytes result in interesting dynamics and lead to the secretion of important cytokines such as HMGB1, IL12, IL10, and IL6." (PMID 35294447, 2022). "The priming of T-cells was inhibited in mice bearing CT26 cancer cells, owing to the depletion of HMGB1 or co-injection of anti-HMGB1 antibody." (PMID 36145510, 2022). "The cancer samples were divided into high‐ and low‐expression groups based on the expression levels of HMGB1." (PMID 35765707, 2022). "NETs also activate a series of TLR9-dependent signaling pathways, such as the MAP kinase pathway and NF-κB pathway, in cancer cells by releasing high mobility group box 1 (HMGB1), thus promoting cell proliferation, adhesion, migration, and invasion." (PMID 36365233, 2022). "Dendritic cells (D) are activated by the high mobility group box 1 (HMGB-1) expressed on necrotic cancer cells." (PMID 35015785, 2022).
cancer (continued). "The results indicate that CRT was exposed on surface of the FAST-treated cancer cells and HMGB1 was released in the culture medium of the FAST-treated cancer cell." (PMID 36329436, 2022). "In mouse and human cancer, Tim-3 acts in DCs to suppress nucleic acid–mediated innate immune responses by interfering with HMGB1-mediated activation of nucleic acid systems." (PMID 35316223, 2022). "The HMGB1-RAGE signaling pathway is an important target for cancer therapeutics in relation to the TME." (PMID 35408786, 2022). "HMGB1 is produced proportional to the number of dendritic cells, necrotic cells, macrophages, cytotoxic cells, and cancer cells and decays naturally." (PMID 35294447, 2022). "On the other hand, in HMGB1-stimulated HCT116 cancer cells, C6 was revealed to suppress the activation of ERK1/2, CDK1, and AKT and the down-regulation of anti-apoptotic XIAP but not c-IAP1, c-IAP2, and Bcl-xL and up-regulate pro-apoptotic Bax and caspase-3/7." (PMID 35408786, 2022). "In vitro studies have shown that NETs induced changes in the inflammatory microenvironment and activated TLR9-dependent pathways in cancer cells by releasing HMGB1, thereby promoting cancer cell adhesion, proliferation, migration and invasion." (PMID 36365233, 2022). "Certain DAMPs, such as a high mobility group box-1 protein (HMGB1), can potentially promote cancer progression." (PMID 36142391, 2022). "Administration of DOX increases HMGB1 expression and induces TNF- secretion via TLR4, whereas HMGB1 released from necrotic cancer cells treated with necrosis inducers increases regrowth and metastasis of residual cancer cells through RAGE activation." (PMID 35340325, 2022). "We observed an increased extracellular HMGB1 release in cancer cells 24 h post-BNCT irradiation, compared to that observed with an equivalent dose of gamma-ray irradiation." (PMID 35336794, 2022). "HMGB1 has been reported to play a role in micrometastasis from the early stages of cancer through EMT and angiogenesis." (PMID 35328684, 2022). "Dying cancer cells secrete several DAMPs such as ATP, a “find-me” signal for DCs; calreticulin; high mobility group box 1 (HMGB1) or type I IFNs." (PMID 36611932, 2022). "HMGB1 released from the nucleus and its subsequent secretion and ATP released from dying cancer cells in the context of ICD, was described as a consensus marker for ICD." (PMID 35959371, 2022). "Recently, it was also reported that in human cervical cancer cells, miR-142-3p targets HMGB1, inducing apoptosis and inhibiting proliferation, migration, and invasion of cancer cells." (PMID 35269471, 2022). "Our results indicate that cancer-derived HMGB1 elevates angiogenesis in ESCC by shifting the balance toward proangiogenic signals in proliferating B cells." (PMID 34617194, 2022). "The secreted HMGB1 induces the matrix metalloproteinase pathway and increases the invasiveness of cancer cells." (PMID 36324584, 2022). "HMGB1 is one of the most abundant RAGE ligands in the inflammatory TME, and overexpression of HMGB1 in cancer cells is near-universal in solid tumors." (PMID 35408786, 2022). "These necrotic GBM cancer cells release high mobility group box 1 (HMGB1) and cyclophilin A that enhance chemoattraction and maturation of dendritic cells (DCs) as initiators of antitumor immunity." (PMID 35280755, 2022). "According to the GEPIA2 web server, using the “Pathological Stage Plot” function, we obtained a close relationship between HMGB1 expression and the pathological stages of cancer with KIRC, SKCM, THCA, LIHC, and LUSC." (PMID 36230798, 2022). "For cancer treatment, further research should pay attention to the role of HMGB1 in immunotherapy and targeted therapy." (PMID 35765707, 2022). "Previously, we found that HMGB1/RAGE signaling is of importance in cancer cell proliferation, survival and escape from apoptosis, and that the cancer cells and platelets are representative sources of HMGB1 release." (PMID 36012397, 2022).